ENSG00000303636 (novel transcript)
Gene: Long non-coding RNA gene on chromosome 14 (103,316,935 to 103,328,813, forward strand). Ensembl gene ENSG00000303636.
Gene Ontology:
Molecular function: structural constituent of ribosome
Cellular component: ribosome